AR (androgen receptor)
Diseases named in the same sentence as AR in open-access papers (continued):
Sharing a sentence is not in itself a finding about the gene and the disease.
breast carcinoma (continued). "For example, the androgen (AR) and estrogen (both ESR1 and ESR2) nuclear hormone receptors are known to be relevant in prostate and breast cancers, and the alpha-type platelet-derived (PDGFRA) and epidermal (EGFR) growth factor receptors are recognised angiogenesis factors." (PMID 22558171, 2012). "The molecular mechanisms of AR signaling pathway in breast carcinoma biology are not clearly understood." (PMID 23272232, 2012). "IGF1R and AR inhibitors are currently tested separately in the clinic in this context, whereas ERBB3 has not previously been linked to the biology of ER+ breast cancer." (PMID 22343619, 2012). "Due to their similar morphology and possible embryologic origin, it is not surprising that ER, PR, and AR expression can be seen in apocrine-eccrine carcinomas as observed in mammary carcinomas." (PMID 23056620, 2012). "MDA-MB-453 represents a molecular apocrine breast cancer, which is estrogen receptor-negative but androgen receptor-positive, and is commonly detected in patients with CS." (PMID 22103913, 2011). "Therefore, cross-regulation between the AR and ERK signaling pathways provides an attractive therapeutic target in molecular apocrine breast cancer." (PMID 21457548, 2011). "Numerous investigators have suggested that the efficacy of MPA at pharmacologic doses in breast cancer treatment is due to activation of AR rather than PR at those doses." (PMID 16457685, 2005). "A new progesterone receptor-negative, androgen receptor-positive human breast cancer cell line, designated Y-AR, was engineered and characterized." (PMID 16457685, 2005). "Furthermore, HER2‐positive breast cancer patients exhibit a positive correlation between AR pathway activity and AR expression status, suggesting potential benefits from AR antagonists in HER2+/AR+ subtypes." (PMID 40703006, 2025). "Recently, it was found that the AR to ER ratio in breast cancer influences the sensitivity to AR-targeted treatments, suggesting the potential utility of enzalutamide in ER+ tumors with a low AR/ER ratio and AR agonists like RAD140 in those with a high AR/ER ratio." (PMID 40244377, 2025). "Notably, AR-driven CLDN8 can activate pro-growth MAPK/AKT signaling in certain contexts, but in ER(+) breast cancer, this may paradoxically reinforce luminal characteristics that endocrine therapy can target effectively." (PMID 40508219, 2025). "Furthermore, we identified nuclear grade, microenvironment heterogeneity, estrogen receptor (ER), androgen receptor (AR), human epidermal growth factor receptor 2 (HER2), Ki-67 antigen, as the most significant histopathological markers of breast cancer recurrence." (PMID 40597870, 2025). "The role of androgens in the pathogenesis of canine mammary tumors is not well established, but some studies suggest that androgens could influence tumor growth through AR-mediated mechanisms." (PMID 40286049, 2025). "Quadruple-negative breast cancers (also known as AR-triple negative (TN) BC) lack the expression of estrogen receptor (ER), progesterone receptor (PR), human epidermal growth factor receptor 2 (HER2), and androgen receptor (AR)." (PMID 40448099, 2025). "Our results claim that, the same as hormonal-receptor-positive breast cancer being affected by hormonal imbalance, TNBC cell lines may also be affected by this imbalance despite the absence of ERα and PR expression and due to the expression of AR and ERβ." (PMID 38338747, 2024). "Herein, we employ an unbiased chromatin immunoprecipitation-based proteomic technique to identify endogenous AR interacting co-regulatory proteins in ER positive and negative models of breast cancer to gain new insight into mechanisms of AR signaling in this disease." (PMID 38317241, 2024). "Therefore, AR expression may be useful for the prognosis of OS for patients with ER-negative and HER2-positive breast cancer." (PMID 38339092, 2024).
breast carcinoma (continued). "Stat5 depletion did not affect AR mRNA and protein levels in AR-positive breast cancer cells, which suggests that Stat5 induction may be tissue-specific." (PMID 38416822, 2024). "However, no PR binding to the AR 5’ UTR was noted in response to synthetic progestogen treatment in breast cancer cells." (PMID 39088439, 2024). "Additionally, due to constraints in the composition of the GWAS database, this study only performed bidirectional two-sample Mendelian randomization analyses on ER+ and ER-breast cancer subtypes, precluding further analysis based on different HER2, PR, or even AR expression statuses." (PMID 39109338, 2024). "Given that our qPLEX-RIME data shows a significant enrichment of ZMIZ1 protein vs the control, was undertaken using a breast cancer cell line, and that we did not detect the presence of AR in our qPLEX-RIME data, this implies AR was not within the ER complex in the experimental conditions used." (PMID 38564418, 2024). "The pioneer factor GATA3 is a well-established ER interacting protein in breast cancer cells that modulates but is not required for ER to bind chromatin, but an interaction between AR and GATA3 has not been previously reported in any tissue or cellular context." (PMID 38317241, 2024). "Likewise, ChIP-seq has been used to expand understanding of AR signaling in this disease, but to date, no one has interrogated multi-subunit protein complexes involving AR in an unbiased manner in breast cancer." (PMID 38317241, 2024). "However, to date, there is no approved AR targeting therapy for breast cancer, which is largely considered to be due to inadequate patient selection criteria for clinical trials." (PMID 38339092, 2024). "In ERα-positive breast cancer, AR positivity (expression at both mRNA and protein levels) was significantly correlated with improved disease-free survival (DFS) and overall survival (OS), and tumors with an AR:ERα positivity ratio of >0.87 had the best outcome." (PMID 38339092, 2024). "AR positive expression is not an independent predictor of HR-/HER2 + breast cancer." (PMID 37099044, 2023). "Here we show for the first time that the AR is a direct positive regulator of RUNX1 gene expression in AR+-TNBC and that RUNX1 transcriptional activity is involved in the CSC-like phenotype and chemoresistance, contributing to tumor progression in this aggressive breast cancer subtype." (PMID 36766786, 2023). "The negative action of X15695 on proliferation of AR+ prostate and ER+ breast cancer, posed the question whether the proliferation of other tumor cells could be inhibited by this compound." (PMID 37520743, 2023). "Whereas in previous reports RIOK1 expression was correlated with hormone receptor status and phosphatidylinositol 3-kinase (PI3K)/AKT signaling in breast cancer and glioma, respectively, no consistent association of RIOK1 mRNA expression with AR and PI3K/AKT target gene sets in PCa was observed." (PMID 37301535, 2023). "To date, AR targeted therapies have not been explored for breast cancer prevention." (PMID 37583424, 2023). "Finally, in HER2+ breast cancer, enzalutamide inhibited growth in trastuzumab-resistant HER2+ breast cancer xenografts, which may be attributed to the cross-talk between AR signaling and HER2 signaling." (PMID 37345085, 2023). "Furthermore, the results from our WGCNA analysis indicated the existence of unknown networks between INO80 and a subset of luminal breast cancer biomarkers, including FOXA1, ESR1, GATA3, TFF1, and AR." (PMID 38020889, 2023). "In addition, unveiling the complicated interactions between AR and the HER2 signaling pathway will further help utilize AR as an attractive therapeutic target of HER2-enriched nonmetastatic breast cancer." (PMID 37085500, 2023). "This is not surprising given that AR functions as a tumour suppressor in ER+ breast cancer." (PMID 37345085, 2023).
breast carcinoma (continued). "They found that patients with high AR/ER (>1.75, third quartile) had higher circulating testosterone levels and significantly worse DFS, which was a result validated in the Cancer Genome Atlas (TCGA) and the Molecular Taxonomy of Breast Cancer International Consortium (METABRIC) databases." (PMID 36556209, 2022). "Further research is needed to reveal the role of AR in luminal B (HER–2 negative) breast cancer." (PMID 36556209, 2022). "Suntag-KRAB repression at the CITED2 enhancers confirms that CI54 most significantly affects transcription, while Cas9-mediated CI54 deletion in the CITED2 expressing AR+ breast cancer cell line MDA-MB453 did not result in a transcriptional decrease, as this cell line does not use enhancer CI54." (PMID 36450752, 2022). "LAR TNBC is an ERα-negative/AR-positive breast cancer and anti-androgens may be effective in its management." (PMID 35013318, 2022). "In our study, AR reactivity was seen mainly in pure apocrine carcinomas or carcinomas with apocrine or histiocytoid features which is compatible with the findings reported by other investigators that molecular apocrine breast cancer is negative for ER and usually expresses AR and FOXA14,33,34." (PMID 35444182, 2022). "Similarly, although Gli3 does not have a direct role in breast cancer, it has been found to cooperate with other genes such as androgen receptor (AR), estrogen receptor (ER) and Eph10A to promote tumorigenesis and invasive phenotypes." (PMID 35846378, 2022). "Therefore, the crosstalk of AR, EGFR, and BRCA1 may affect the significance of AR in breast cancers, especially in TNBC." (PMID 35053220, 2022). "The increased expression of APOD could predict poor prognosis in patients with breast cancer independent of the expression of ER α and AR." (PMID 34983559, 2022). "In recent years, many studies have confirmed that AR plays an important role in the occurrence and development of breast cancer, but this role is not directly induced by AR independent signaling pathway, but closely related to multiple pathways, such as HER-2, wnt, ERα and MAPK." (PMID 35311116, 2022). "Additionally, a cohort of breast cancer patients with increased expression of the androgen receptor gene (AR) showed a paucity of statistically significant negative correlations between glycolysis and immune genes." (PMID 36505421, 2022). "Inhibition of AR signalling could be involved in the described pro-metastatic activity of ESR1 mutants and is concordant with the tumour suppressive effects of AR in ER+ breast cancer comprehensively demonstrated recently." (PMID 36198774, 2022). "AR agonists, such as the natural ligand dihydrotestosterone (DHT) or the Selective Androgen Receptor Modulator (SARM) enobosarm (lacking virilising activity), exert an anti-proliferative effect in normal mammary epithelium, as well as in ERα+ breast cancer, both in vitro and in vivo." (PMID 35008851, 2021). "AR is not a good biomarker for the existing subtypes of breast cancer, even though its expression could be used to define subtype stratification." (PMID 33915941, 2021). "In addition, BC-N102 suppresses both ligands mediated (classical) and non-ligand mediated (alternative) pathways of ER, AR, and PR activation while mediating the activation of MR signaling in breast cancer." (PMID 34421361, 2021). "Therefore, here we attempt to present the complex aspects of SR molecular function in breast cells, including an in-depth description of PR, AR, GR, MR and VDR and their vast interactomes, understanding of which is crucial for developing new approaches in breast cancer endocrine therapy." (PMID 34638264, 2021).
breast carcinoma (continued). "Whether the benefit was limited to patients with basal breast cancer lacking AR expression was not determined in these studies." (PMID 34667258, 2021). "Because p68 siRNA decreases the levels of AR, and p68 regulates PDGFR-β upon PDGF stimulation, we therefore believe that there is regulatory axis of p68-PDGFR-β-AR in PDGF-BB and androgen signaling, wherein p68 and PDGFR-β co-regulate AR expression in breast cancer cells." (PMID 34659545, 2021). "Since AR has been proposed as an important regulator of carcinogenesis in a subset of triple negative breast cancers (TNBC), the interplay between PARP7 and AR could be studied to further understand the role of PARP7 in breast cancer." (PMID 33799807, 2021). "Other studies show that in certain cancer lines (e.g., MCF-7) and in certain ERα-negative breast cancers (the molecular apocrine subtype) AR can successfully mimic the cistrome of ER and be pro-proliferative, as it is antiproliferative in luminal breast cancers." (PMID 34638264, 2021). "Notably, in the breast cancer cell lines, androgen receptor (AR) is weakly, positively correlated with PART1, whereas in breast cancer patient tumors, AR is significantly negatively correlated with PART1, potentially suggesting a cell culturing-dependent effect." (PMID 34072264, 2021). "To assess the potential clinical relevance of PART1/AR signaling in breast cancer, we assessed the correlation of PART1 expression with the androgen signaling gene panel (containing 10 genes, from cBioPortal) across breast cancer subtypes in two breast cancer patient tumor datasets." (PMID 34072264, 2021). "While AR is currently not routinely assessed immunohistochemically in biopsies and surgical excision specimens from our breast cancer patients, it is in fact the most widely expressed hormone receptor in all stages of breast cancer." (PMID 34638457, 2021). "To date, the combination therapy of PARPi with anti-AR therapy has not been tested in breast cancer; however, this combination may be an effective treatment strategy for AR+ BC patients, especially those with BRCA mutated tumors." (PMID 33062889, 2020). "Additionally, in breast cancer models, the presence of an ARE −383 to −377 base pairs upstream of the ERβ promoter region results in enhanced control of ERβ expression as a result of AR signaling." (PMID 33062889, 2020). "Although [18F]FDHT PET showed relatively low visual agreement, presumably a result of the low AR expression and consequently low TBR in patients with breast cancer, there was good quantitative agreement between observers, acceptable for further [18F]FDHT PET imaging studies in breast cancer." (PMID 32307594, 2020). "It is not yet clear what the clinical significance may be of the AR on the cell surface of breast cancer cells." (PMID 32326308, 2020). "However these studies did not provide evidence on prognostic relevance of AR in different breast cancer subtypes." (PMID 32928183, 2020). "A phase II clinical trial evaluating bicalutamide, a first-generation AR antagonist, in AR-positive/ERα-negative/PgR-negative advanced breast cancers, showed a clinical benefit rate of 19% at 6 months and a median progression-free survival duration of 12 weeks." (PMID 31952272, 2020). "Up to now, no consequences for therapy decisions based on AR expression in breast cancer therapy could be drawn." (PMID 31728025, 2019). "Hence, the synergy between enzalutamide and USP14 inhibition in antitumor effect on breast cancer also may be attributable to additional tumor suppressing actions from USP14 inhibition, beyond suppressing AR signaling." (PMID 31126320, 2019). "Additionally, we further explored the relative gene expression of other important hormonal receptors in breast cancer, such as estrogen receptor beta (ESR2), progesterone receptor (PGR) and androgen receptor (AR), concomitantly with estrogen receptor alpha (ESR1)." (PMID 31817155, 2019).
breast carcinoma (continued). "Androgens and AR have been reported to facilitate tumor stemness in some cancers; a process which may be mediated through genomic or non-genomic actions of the AR, with the latter mechanism being relatively unexplored in breast cancer." (PMID 30416486, 2018). "Additional breast cancer, Gene Expression Omnibus series (GSE) files GSE37751 and GSE46581 that contained annotated race variables as well as HR status showed a significantly lower expression of AR in tumors of AA women compared to those of White women in both non-TNBC and TNBC tumors as well." (PMID 29912871, 2018). "Moreover, functional studies identified an interplay between AR and SRARP in breast cancer cells." (PMID 29577611, 2018). "However, there are several reports that breast carcinoma expresses AR through a mechanism independent of apocrine metaplasia." (PMID 28965222, 2018). "Recent studies showed that AR is widely distributed in primary and metastatic breast cancers, with 60–80% of all, 90% estrogen receptor (ER)-positive, 50% human epidermal growth factor receptor 2 (HER2)-positive, and 75% triple negative (TNBC) breast cancers being AR-positive." (PMID 29713287, 2018). "Although AR expression is acquired in many breast cancer cases, its expression could not define a unique subtype." (PMID 30279965, 2018). "Furthermore, non-genomic AR signaling has been reported in the sertoli cells of the testes, fibroblasts, osteoblasts and osteocytes, stromal cells, and breast cancer cells." (PMID 30416486, 2018). "Statistically, there is significant difference between AR-positive and AR-negative patients and the expression of classical breast cancer biomarkers ER, PR, HER2 in the overall population, as well as in African American patients; this was even more pronounced in TNBC." (PMID 29912871, 2018). "However, despite these emerging data, the role of AR in breast cancer is still not fully elucidated and the biology of AR in breast cancer remains incompletely understood." (PMID 30547831, 2018). "However, a comprehensive analysis of AR expression within all breast cancer subtypes or stratified by race has not been reported." (PMID 29912871, 2018). "A major hurdle in successful utilization of these drugs in the treatment of breast cancer is our lack of understanding at what drives this dichotomy—what makes some AR positive tumors behave so differently and respond in such a different way to the same treatment?" (PMID 30416486, 2018). "Although a clinical threshold that determines AR positivity and negativity for breast cancer patients has not widely established, this is the first report to evaluate the expression of AR, and link the absence of AR to a distinctive gene signature stratified by race." (PMID 29912871, 2018). "Together, we have shown that AR is not a good biomarker for the existing subtypes of breast cancer, although its expression could be used to define further subtype stratification." (PMID 30279965, 2018). "The dynamics between AR and ER in breast cancer are not just specific to DNA binding." (PMID 30416486, 2018). "Although the methods for detecting ESR1 or HER2 in breast cancer biopsies by immunohistochemistry are well established, AR immunohistochemistry performed on tumor biopsies is not routine or standardized leading to a wide variation in the reported number of AR-positive breast cancer cases." (PMID 30279965, 2018). "However, AR signaling can operate without interacting with ERα at cellular level since many AR-positive/ERα-negative cells exist in different subtypes of breast cancer." (PMID 28474005, 2017). "Especially the high AR discordance we found is new and very relevant, since AR-targeted therapies are recently gaining interest for the treatment of ERα-negative and endocrine therapy resistant breast cancer." (PMID 28903441, 2017). "There is yet no consensus on whether AR antagonists or agonists are preferable as targeted treatments in any breast cancer subtype." (PMID 28643022, 2017).